CYP3A4 (cytochrome P450 family 3 subfamily A member 4)
Diseases named in the same sentence as CYP3A4 in open-access papers (continued):
Sharing a sentence is not in itself a finding about the gene and the disease.
breast carcinoma (continued). "Although very minimal, this demonstrates that the mechanism of CYP3A4-mediated ifosfamide metabolism is present in breast cancer microsomes." (PMID 31309254, 2019). "Despite the large variability in reported expression frequencies, some larger studies suggest that the CYP3A4 protein is present somewhere between 20 and 55% of breast cancer tissues." (PMID 31309254, 2019). "CYP3A4 plays a key role in the metabolism of important drugs used in breast cancer treatment which include anastrozole, letrozole, exemestane, tamoxifen, cyclophosphamide, paclitaxel and docetaxel." (PMID 30914849, 2018). "CYP3A4 is an important enzyme in the metabolism of many important drugs used in the treatment of breast cancer." (PMID 30914849, 2018). "We note that the controversy remains over the influence of the CYP3A4*1B gene on the genesis of breast cancer." (PMID 30336495, 2018). "A multiplex PCR-RFLP method was successfully developed for simultaneous detection of CYP3A4*4, CYP3A4*18B and CYP3A4*22 in a population of post-menopausal breast cancer patients." (PMID 30914849, 2018). "Of the 168 breast cancer specimens immunostain with CYP3A4 protein specific antibody, 131 (78.0 %) were low expression, and 37 (22.0%) were high expression." (PMID 28418906, 2017). "To identify a potential role for CYP3A4-mediated EET production in TAM-resistant breast cancer cells, we used ketoconazole, azamulin (chemical CYP3A4 inhibitors) and 14,15-EEZE (an EET antagonist)." (PMID 29050342, 2017). "Because CYP3A4 displays a high ability of AA epoxygenase in breast cancer, we next determined the levels of EETs in MCF-7 and TAMR-MCF-7 cells." (PMID 29050342, 2017). "In our study, CYP3A4 was overexpressed in TAM-resistant breast cancer cells, and its enzymatic inhibition significantly reduced cell proliferation and induced synergistic apoptosis with 4-hydroxytamoxifen." (PMID 29050342, 2017). "Our results support explicating the selective 11,12-EET biosynthesis through the up-regulation of CYP3A4 in TAM-resistant breast cancer." (PMID 29050342, 2017). "It has been reported that CYP3A4 is expressed in approximately 80% of human breast cancers, and that enzyme expression correlates with decreased overall survival in breast cancer." (PMID 29050342, 2017). "Our findings suggest that the CYP3A4-mediated EET pathway represents a potential therapeutic target for the treatment of tamoxifen-resistant breast cancer." (PMID 29050342, 2017). "The ambiguous roles of CYP2B6 and CYP3A4 noted by this study warrant investigations focused on regulation of their expression and posttranscriptional processing specifically in breast carcinomas." (PMID 25526449, 2014). "AKR1C2 and CYP3A4 were studied in more detail using breast carcinoma model MDA-MB-231 (triple negative) cell line in vitro." (PMID 25526449, 2014). "Following activation of hPXR, the expression of MDR1 and CYP3A4, two possible mediators of hPXR-mediated drug resistance in breast cancers was increased." (PMID 23599746, 2013). "We studied the association of the functionally significant variant alleles of CYP3A4, CYP3A5, CYP2B6, CYP2C8, CYP2C9 and CYP2C19 with the clinical response to neoadjuvant chemotherapy in breast cancer patients." (PMID 22702493, 2012). "Here, we studied the association of functionally significant variant alleles of CYP3A4, CYP3A5, CYP2B6, CYP2C8, CYP2C9 and CYP2C19 with the clinical response to neoadjuvant chemotherapy in breast cancer patients." (PMID 22702493, 2012). "We found that women who received cyclophosphamide-based adjuvant chemotherapy for breast cancer and had the CYP3A4 *1B*/*1A genotype had significantly worse DFS than those who were CYP3A4 *1A/*1A wild-type (HR 2.44, 95% CI 1.52, 5.14)." (PMID 20459744, 2010). "Reverse transcription–PCR analysis demonstrated the presence of CYP3A4 mRNA in 15% and 75% of tested breast cancer samples, respectively." (PMID 14970873, 2004).
breast carcinoma (continued). "The results demonstrate that all mammary tumours (n=11) reveal CYP3A4 expression; contents varied from 0.5 to 63 pmol mgprotein−1." (PMID 14970873, 2004). "Collectively, these findings suggest that LRRC8A inhibition may represent a therapeutic strategy to overcome chemoresistance by repressing MRP3 and/or CYP3A4 expression in breast cancer stem cells." (PMID 41898509, 2026). "We measured the association between pharmaceutical inhibition of CYP2D6, CYP2C19, and CYP3A4 and recurrence in a large cohort of tamoxifen‐treated Danish premenopausal breast cancer patients using a Bayesian joint modeling approach and compared this with traditional Cox regression models." (PMID 40364655, 2025). "Previously, several studies had reported that the rs2242480 polymorphism of CYP3A4 gene had a significant impact on the risk of breast cancer, but these studies yielded negative results." (PMID 41242742, 2025). "Clinical trials have also examined specific CYP isoforms like CYP3A4 in breast cancer settings." (PMID 40723371, 2025). "Our study was not the first case-control study to verify the impact of CYP3A4 gene SNP on the risk of breast cancer." (PMID 41242742, 2025). "To date, results on relationship between CYP3A4 gene polymorphism were limited and inconclusive, and no study focused on the influence of CYP3A4 gene-obesity interaction on breast cancer risk, especially in Chinese women." (PMID 41242742, 2025). "Moreover, CYP3A4 is involved in the synthesis of epoxyeicosatenoic acids (EETs) and facilitates the growth of breast cancer cells via STAT3 activation mediated by EET." (PMID 38297388, 2024). "CYP3A4 expression has been shown to correlate with poor overall survival in breast cancer." (PMID 35215292, 2022). "We already mentioned that CYP3A4 participates in breast cancer progression by stimulating angiogenesis through VEGF activation and by promoting cancer cell proliferation through the activation of PI3 kinase–AKT and STAT3 pathways, in part via the synthesis of (+/−)-14,15-EET." (PMID 36359206, 2022). "Moreover, more studies should investigate the potential of CYP3A4*22 in modifying the experience of hot flashes among breast cancer patients who are undergoing adjuvant endocrine therapies." (PMID 34006247, 2021). "Furthermore, higher expression of CYP3A4 has been shown to be related to tumour progression in ER+ breast cancer cells, in part via the synthesis of epoxyeicosatrienoic acids." (PMID 33809117, 2021). "CYP3A4 is abundantly expressed and plays major role in metabolising 60% of the marketed drugs including chemotherapy used to treat breast cancer patients such as CPA, docetaxel, paclitaxel, etoposide, irinotecan, imatinib, lapatinib, trastuzumab emtansine and tamoxifen." (PMID 33809117, 2021). "CYP3A4 is currently indicated for the treatment of ovarian and breast cancer." (PMID 32547867, 2020). "Their analysis showed expression in 25% of mammary tumor samples screened for CYP3A4/5." (PMID 31309254, 2019). "Our study is the first to simultaneously determine the genotype of CYP3A4*4 A>G, CYP3A4*18B G>A and CYP3A4*22 C>T that may be useful as possible biomarkers to predict breast cancer response to treatment." (PMID 30914849, 2018). "We did not observe a relationship between the CYP3A4*1B gene polymorphism and the occurrence of breast cancer." (PMID 30336495, 2018). "The main results of the present study suggest that the G allele and the GG genotype of the CYP3A4*1B gene do not play a key role in breast cancer development." (PMID 30336495, 2018). "Cytochrome P450 (CYP) 1A2 and CYP3A4 may play a role in the differentiation of clinical outcomes among breast cancer women." (PMID 28418906, 2017). "Hence, these results highlight a pivotal role of CYP3A4 up-regulation in multiple regulation of cancer aggressiveness in TAM-resistant breast cancer." (PMID 29050342, 2017).
breast carcinoma (continued). "CYP epoxygenases, including CYP2C8, 2J2, 2C9, and CYP3A4, have the capacity to synthesize EETs and may be involved in breast cancer progression." (PMID 29050342, 2017). "To the best of our knowledge, we are the first to analyse the association of the four CYP450 SNPs, including rs11636419, rs17861162, and rs2470890 in the CYP1A2 gene and rs12333983 in the CYP3A4 gene, with the clinicopathological features and prognosis of breast cancer patients." (PMID 28418906, 2017). "CYP1A2 and CYP3A4 protein expression was shown in 168 breast cancer tissues." (PMID 28418906, 2017). "However, no study focused on the influence of CYP3A4 gene-obesity interaction on breast cancer risk yet, especially in Chinese women." (PMID 41242742, 2025). "However, CYP3A4 might not only induce breast cancer via hydroxylated forms of estrogen but also by the production of epoxyeicosatrienoic acids through the arachidonic metabolism pathway." (PMID 35215292, 2022). "It has been demonstrated that high expression of CYP3A4/5 at mRNA and protein levels in tumor tissues of the mammary gland correlates with lymph node metastasis (lymph node status) and may be a key sign of an unfavorable prognosis of breast cancer." (PMID 36359206, 2022). "In addition, assessment of CYP3A4, CYP3A5 and UGT1A4 variant alleles and knowledge about their allelic frequency in the Croatian population may lead to personalized breast cancer therapy." (PMID 32456253, 2020). "After adjusting for oral contraceptive use and family history of breast cancer, the presence of the G allele and the GG (AG + GG) genotype of the CYP3A4*1B polymorphism was not directly associated with tumor occurrence (OR = 1.151; 95%CI: 0.714–1.856; p = 0.564)." (PMID 30336495, 2018). "In addition, CYP3A4, a major P450 in humans, is involved in the metabolism of half of all currently used drugs including AsIII and docetaxel, one of the most commonly used chemotherapeutics for breast cancer." (PMID 30123091, 2018). "Breast cancer spheroids (BT474, HCC1954, EFM192A) were more resistant to the drugs neratinib and docetaxel, due to the increase in both CYP3A4 activity and the expression of two membrane transporters associated with resistance (PGP and BCRP)." (PMID 38201092, 2023). "Breast cancer can be prevented by eating foods that change the activity of certain cytochrome P450 enzymes, including CYP1A1, CYP1A2, CYP1B1, CYP2B6, CYP3A4, CYP19A1, and CYP24A1." (PMID 36571647, 2022). "Cytochrome P450s (CYPs), mainly CYP3A4, and several oxidoreductases are responsible for Phase I metabolism of doxorubicin (DOX), an anthracycline widely used in breast cancer (BC) treatment." (PMID 36360213, 2022). "Further studies on whether CYP3A4*22, or other SNPs of CYP3A4, could affect the experience of hot flashes would be worthwhile, contributing further evidence on whether CYP3A4*22 can be used as a biomarker to regulate this symptom among breast cancer patients undergoing adjuvant endocrine therapies." (PMID 34006247, 2021). "Conversely, miR148a increases levels of CYP3A4 and CYP2C19 and is downregulated in a number of cancers, including most of the lower gastrointestinal (GI) tumors, along with head & neck cancers, breast cancer, lung cancer and melanoma." (PMID 31963461, 2020). "Schmidt and colleagues, in addition to detecting CYP3A4 and CYP2C9 in breast cancer microsomes, also investigated the ability of these microsomes to metabolize ifosfamide." (PMID 31309254, 2019). "Our investigations of mistletoe interactions with CYP3A4/5 and CYP2D6, secure recommendations for the use of mistletoe extracts to treat cancer related-fatigue in breast cancer patients receiving tamoxifen." (PMID 30658716, 2019). "Specific roles for CYP3A4 and CYP19A1 in breast cancer therapy response have been reviewed, but only preliminary considerations have been made for modeling the concurrent and opposing activities of these enzymes on therapies within the same treatment regimen." (PMID 29783934, 2018).
breast carcinoma (continued). "Our data suggest that Pin1 acts as a key mediator for the effects of CYP3A4-derived 11,12-EET biosynthesis in TAM-resistant breast cancer." (PMID 29050342, 2017). "The CYP genes with the lowest expression in the TCGA breast cancer cohort were: CYP1A2 (0.010), CYP3A43 (0.029), CYP3A7 (0.033), CYP2C9 (0.044) and CYP3A4 (0.044)." (PMID 28684774, 2017). "Here, we found that CYP3A4 expression and its epoxy-product, 11,12-epoxyeicosatrienoic acid (11,12-EET) was enhanced in tamoxifen (TAM)-resistant MCF-7 (TAMR-MCF-7) breast cancer cells compared to control MCF-7 cells." (PMID 29050342, 2017). "Our research revealed that CYP3A4 is overexpressed and plays an important role in cell proliferation, angiogenesis, and migration in TAM-resistant breast cancer cells, in part through 11,12-EET biosynthesis." (PMID 29050342, 2017). "Tamoxifen, a common anti-estrogen breast cancer medication, is a prodrug that undergoes bioactivation via cytochrome P450 enzymes, CYP2D6 and to a lesser degree, CYP3A4 to form the active metabolite endoxifen." (PMID 27169677, 2016). "Mechanisms of action of AKR1C2, AKR7A3, CYP2B6, CYP3A4, and CBR1 should continue to be further followed in breast carcinoma patients and models." (PMID 25526449, 2014). "Moreover, Miyoshi and colleagues suggest using intratumoral levels of CYP3A4/7 mRNA as predictors of response to antineoplastic drugs such as docetaxel in the treatment of breast cancer; and further involvement of the CYP3A family in drug clearance may have subsequent effects on patient prognosis." (PMID 24690092, 2014). "In this descriptive study, correlations were examined between concentrations of tamoxifen metabolites and genotypes for CYP2D6, CYP3A4, CYP3A5, SULT1A1, SULT1A2 and SULT1E1 in 135 patients with estrogen receptor-positive breast cancer." (PMID 23922954, 2013). "In comparison to CYP3A4, CYP2C8 transcripts were detected at variable levels in our breast carcinoma samples and were preferentially high in tumors with low proliferation rates, as indicated by low Ki67 scores." (PMID 23935969, 2013). "In contrast, astemizole inhibited basal CYP3A4 gene expression and blocked calcitriol-dependent CYP3A4 induction, in a similar manner as that observed for CYP24A1 in breast cancer cells." (PMID 22984610, 2012). "Using a polyclonal anti-human CYP3A4 antibody (detecting CYP34A, 3A5 and 3A7) and recombinant CYP3A4 as a standard, we detected and quantified CYP3A by Western Blotting in all 11 tested breast cancer samples." (PMID 14970873, 2004). "For this purpose, we investigated the expression of CYP3A4, CYP2C9 and CYP2B6 in breast cancer tissue using Western Blotting." (PMID 14970873, 2004). "Ribociclib (RIBO), a first-line treatment for hormone receptor-positive/human epidermal growth factor receptor 2 negative (HR+/HER2−) advanced breast cancer, is an inhibitor of CYP3A4, P-gp, and BCRP." (PMID 40231674, 2025). "In this research, we found that a high level of CYP3A4 in MCF 7 cells could be reduced by Narciclasine treatment, suggesting a new target drug for breast cancer treatment." (PMID 38215156, 2024). "In this study, two traditional machine learning models established using the PLS-DA and AdaBoost algorithms and a novel machine learning model established using the LGBM algorithm were applied to predict the ADMET properties named Caco-2, CYP3A4, hERG, HOB, and MN of anti-breast cancer compounds." (PMID 36903569, 2023). "However, in clinical breast cancer trials, KCZ is typically used to prevent the clearance of the primary therapeutic through CYP3A4 modulation." (PMID 36077791, 2022). "For instance, exogenous miR148a could be administered to boost its levels and effect on CYP3A4 and CYP2C19 in GI tumors, head & neck cancers, breast cancer, lung cancer and melanoma." (PMID 31963461, 2020).
breast carcinoma (continued). "To obtain a more clinically relevant measure of protein expression levels, we randomly selected clinical paraffin-embedded tumor samples representative of all the breast cancer subtypes and subjected them to IHC analysis against CYP2C19/9, CYP2J2, CYP3A4 and sEH antibodies." (PMID 31072371, 2019). "Our findings suggest that CYP3A4 inhibitors and EET antagonists may serve as novel therapeutic agents for the treatment of TAM-resistant breast cancer." (PMID 29050342, 2017). "In fact, in this study, calcitriol stimulated CYP3A4 expression both in the liver and breast cancer cells, suggesting a negative feedback control mechanism; which, interestingly, was dampened by astemizole." (PMID 22984610, 2012). "Some similar studies showed that CYP1A2 and CYP3A4 could be induced in human hepatocytes exposed to BDE-99 and BDE-209, and these results were also supported by the study using human MCF-7 breast cancer cells exposure to PBDEs." (PMID 23554634, 2010). "The predictions revealed that the mechanism of sinapic acid in breast cancer may be due to multiple pathways and proteins like β-catenin, PRKCA, CASP8, and cytochrome enzymes (CYP1A1 and CYP3A4); the majorly regulated pathway was predicted to be “Pathways in cancer”." (PMID 38081857, 2023). "The predictions revealed that the mechanism of sinapic acid in breast cancer may be due to regulation of multiple proteins like CTNNB1, PRKCA, CASP8, SIRT1, and cytochrome enzymes (CYP1A1 & CYP3A4); the majorly regulated pathway was predicted to be ‘Pathways in cancer’." (PMID 38081857, 2023). "In addition, it has been shown that the pharmacokinetics of paclitaxel, which is also a substrate of CYP3A4, was not affected when given in combination with trastuzumab emtansine in breast cancer patients." (PMID 34349115, 2021). "We used vilazodone for these experiments because unlike some other SSRI vilazodone does not inhibit CYP2D6, which is required for the conversion of the breast cancer pro-drug tamoxifen into its active metabolite endoxifen, nor does it affect CYP3A4 activity, which metabolizes many chemotherapeutics." (PMID 28404880, 2017). "Another study by Nagaoka reported that tamoxifen activates CYP3A4 and MDR1/P-glycoprotein genes through steroid and xenobiotic receptor (SXR), a member of nuclear hormone receptors, which may affect tamoxifen metabolism and transport in breast cancer cells." (PMID 26981116, 2016). "The overexpression of CYP3A4 has been reported in breast cancer but not in gastric cancer." (PMID 20187983, 2010). "Indeed, docetaxel and paclitaxel both undergo liver metabolism through CYP3A4; therefore, if curcumin had inhibited this isozyme, one would have expected a potentiation of taxane anticancer effects in metastatic prostate and breast cancer patients but unfortunately, this has not occurred." (PMID 37111761, 2023). "Moreover, single exposure of 4-hydroxytomoxifen (0.3 and 3 μM) in MCF-7 cells marginally increased the protein expression of CYP3A4, which imply that CYP3A4 induction in TAM-resistant breast cancer cells may results from long-term adaption of cells to 4-hydroxytamoxifen." (PMID 29050342, 2017). "Critically, certain drugs used to treat advanced stages of breast cancer such as paclitaxel display little or no cytotoxic activity after metabolism by CYP2C8 and CYP3A4." (PMID 33809117, 2021).